BCRP3 (BCR pseudogene 3 )
Synonyms: BCR3; BCRL3; BCRL6
Gene: Long non-coding RNA gene on chromosome 22 (24,632,820 to 24,653,362, forward strand). Ensembl gene ENSG00000215481.
Diseases named in the same sentence as BCRP3 in open-access papers:
BCRP3 is named in the same sentence as 6 diseases in open-access papers, as found by Europe PMC text mining. Sharing a sentence is not in itself a finding about the gene and the disease. The quoted sentences say what the papers report.
colorectal cancer (1 paper, 2022). A primary or metastatic malignant neoplasm that affects the colon or rectum. "While overexpression of BCRP3 in HCT116 human colorectal cancer cell line did not affect cell viability at the basal state, it significantly increased cell viability upon treatment with a chemotherapeutic drug 5-FU." (PMID 35538574, 2022).
cancer (1 paper, 2022). A tumor composed of atypical neoplastic, often pleomorphic cells that invade other tissues. "By analyzing TCGA data sets, we identified lncRNA BCRP3 based on its lower expression in tumor than normal tissues in many cancer types, including colon, esophagus, brain, skin, stomach, testis, kidney, lung, ovary, prostate, and liver." (PMID 35538574, 2022). "The downregulation of BCRP3 in many cancer types suggested its role in tumor suppression." (PMID 35538574, 2022).
metabolic disorders (1 paper, 2024). "The role of LOC124905962, EXOC3L4, BP11-795H16.2, and BCRP3 in metabolic disorders has not been well-documented yet." (PMID 38997780, 2024).
tumor (1 paper, 2022). "BCRP3 was identified based on its downregulation in many types of tumor tissues, compared with the normal tissues." (PMID 35538574, 2022). "However, whether BCRP3 plays a suppressive role in tumor initiation through its autophagy-enhancing function remains unclear." (PMID 35538574, 2022). "Studying the tumor-initiation function often requires the utilization of genetically modified mouse models, but the lack of murine homologue of BCRP3 precludes such study." (PMID 35538574, 2022).
BCRP3 also shares sentences with these, for which no sentence is quoted: lung adenocarcinoma (1 paper); lymph node metastasis (1).